JAG1 (jagged canonical Notch ligand 1)
Diseases named in the same sentence as JAG1 in open-access papers (continued):
Sharing a sentence is not in itself a finding about the gene and the disease.
tumor (continued). "Furthermore, these data suggest that miR-34b may suppress tumor growth through the suppression of cyclin D1 and JAG1 expression." (PMID 22113133, 2011). "We found that TGFB1/EGFR, LTA/LTBR, CD46/JAG1, and AREG/EGFR ligand‐receptor pairs were stronger in CD4+ T cell‐Plac1+ tumor cells than in CD4+ T cell‐Plac1− tumor cells, among which LTA/LTBR expression was highly specific for Tregs and Plac1+ cells." (PMID 40056047, 2025). "JAG1 knockdown can inhibit the proliferation, invasion and migration of NPC cells and inhibit tumor growth." (PMID 39744570, 2025). "At the HGIN stage, these cells recruit normal fibroblasts through JAG1-NOTCH1 signaling, inducing their conversion to CAFs and establishing CAF–Epi niches at the tumor margin that protect tumor cells against immune surveillance." (PMID 41255572, 2025). "In the context of tumor immunity, TNBC cells secrete factors that induce Jag-1 expression in MDSCs through the NFκB-p65 pathway." (PMID 39735530, 2024). "Histological analysis showed that the Jag1/2 KO mice exhibited various features of SCC, including “pearl-like” tissue structures and spindle-shaped tumor cells." (PMID 38750026, 2024). "Our study also demonstrates that JAG1 affects the proliferation of LGG cell lines and PDL1 expression, thus influencing tumor development." (PMID 38022677, 2023). "We observed that JAG1 and JAG2 showed potential as therapeutic targets in MM, as their silencing resulted in a reduction in the tumor burden." (PMID 37834003, 2023). "It has been described a dual role for the Notch receptor (Notch 1–4)-ligand (JAG1, JAG2, DLL1, DLL3 and DLL4) pathways as oncogenic or tumor suppressors." (PMID 36745330, 2023). "The results showed that most signal flows in the JAG1 positive samples was stronger, including: SPP1 and SELL signal flow, which related to immunosuppressive microenvironment, and tumor angiogenesis-related pathway: NOTCH, VEGF, FGF signal flows." (PMID 36923423, 2023). "The Notch ligands, JAG1 and DLL4, are key factors affecting the interaction of tumor cells with their neighbors and are involved in angiogenesis." (PMID 38203424, 2023). "Taken together, these in vivo results indicated that the expression of JAG ligands was crucial for MM growth, and that the conditional knockout of JAG1 and JAG2 ligands significantly reduced the tumor burden in our MM xenograft model." (PMID 37834003, 2023). "Interestingly, metastatic cells cultured on Jag1 expressed higher levels of Hes1, a target gene that has high expression in cells derived from the primary tumors, while exposure to Jag2 increased expression of Hey1 in both primary tumor and metastasis-derived cells." (PMID 37202533, 2023). "We used tumour tissues from nude mice for the WB assay and found that CCNB2 was correlated with JAG1 expression." (PMID 35349480, 2022). "Interestingly, we have also identified JAG1 as one of the brain-metastatic-specific genes in our analysis, assuming that BC cell-secreted JAG1 might also act paracrinally as well as autocrinally on ECs and tumor cells, respectively." (PMID 35163822, 2022). "Secondly, we indicated a novel signaling pathway in which laminin promotes tumor cells proliferation and migration via integrin α6β4/TRB3/JAG1/Notch axis." (PMID 35585515, 2022). "We demonstrated that the constitutive processing of the Jagged1 protein is a critical event able to convert the proto-oncogene Jag1-FL in a novel Jag1-ICD oncogene, whose function plays an important role in sustaining tumor progression in vivo." (PMID 35847908, 2022). "Immunohistochemistry showed that JAG1 expression was higher in HCC tissues than in paracancerous tissues and was related to tumour size and number and tumour thrombus formation." (PMID 35349480, 2022). "We demonstrated that Kras-induced Jagged1 processing is a critical event able to convert the proto-oncogene Jagged1 full length (Jag1-FL) in a novel Jag1-ICD oncogene, whose function plays an important role in sustaining CRC tumor progression." (PMID 35847908, 2022).
tumor (continued). "The results showed that increased CDC42, CDH2, ERBB2, JAG1, YAP1, and YWHAZ were found in the tumor tissues." (PMID 35340237, 2022). "According to the expression patterns of Dll4 and Jag1, the HCC tissues were divided into two areas (#1 and #2), which represented the peripheral and intrinsic regions of the tumor, respectively." (PMID 35064244, 2022). "Among that, the protein expression of TNFRSF21, JAG1, and SPP1 were evidently up-regulated in tumor than normal tissues." (PMID 36274838, 2022). "It has been found that OS tumor cell-intrinsic CSF1R can enhances cell proliferation and metastasis by CSF-1R/JAG1 axis or ERK signaling pathway." (PMID 35078433, 2022). "Therapy resistance pathways are potentially regulated by JAG1/Notch3-mediated crosstalk between CAFs and BC cells, through the expansion of CD44+CD24 low tumor-initiating and therapy-resistant cells." (PMID 35682974, 2022). "We analyzed JAG1 expression in two published human gene expression data of matching pairs of PDAC and adjacent non-tumor tissue." (PMID 33268505, 2021). "As reported, miR-26b-5p is a tumor suppressor and modulator in cell cycle regulation that targets different genes, including CCND2, PLOD2, JAG1, MAP3K9 and KPN2." (PMID 34488538, 2021). "Antibodies targeting individual Notch receptors and ligands (i.e., JAG1, DLL4) have been developed, showing anti-tumor efficacy against different types of cancers in preclinical studies, with manageable toxicity profiles." (PMID 34439228, 2021). "In HNSCC, some attention has been granted to JAG1 and JAG2, which were found overexpressed in some tumours." (PMID 34944837, 2021). "JAG1-mediated Notch signaling induces neovascularization and sprouting angiogenesis, while DLL4-mediated Notch signaling inhibits tumor angiogenesis." (PMID 34195229, 2021). "It has been shown that in BCC tumor regions, the expression of NOTCH1, DLL1 and JAG1 is lowered in comparison to physiological healthy regions, the basal layer." (PMID 32796631, 2020). "On the other hand, a larger Notch1 decoy, N11–24, recapitulated the effects of inhibiting either JAG1 or DLL4 or both, depending on the tumor microenvironment and in vitro angiogenesis model used." (PMID 32922403, 2020). "RNA‐seq analysis revealed the tumor over‐expressed several genes compared to normal tissue, including components of the Notch signaling pathway, NOTCH3 and JAG1." (PMID 32652895, 2020). "In turn, upregulation of Zeb1 in tumor cells increases VEGFA production and reciprocally induces endothelial Jag1 to create a positive feedback loop." (PMID 33046710, 2020). "CXCL5, ELN, JUN, and FGFR4 were highly expressed in normal tissues, while PLAU, RNASE7, JAG1, SPP1, and TNFRSF18 were highly expressed in tumor tissues." (PMID 32699529, 2020). "In turn, ectopic Zeb1 in tumor cells increases VEGFA production and reciprocally induces endothelial Jag1 in a paracrine manner." (PMID 33046710, 2020). "Based on our findings, we propose that endothelial cells within the tumor function as a CSC niche by directly providing Notch1 ligands, such as Jag1, to the Notch1 receptors expressed in adjacent breast CSCs to elevate Zeb1 expression via a juxtacrine effect." (PMID 33046710, 2020). "JAG1 overexpression has been shown to induce AML in mice, whereas NOTCH1, JAG1, and the main Notch target gene HES1 are overexpressed in AML-MSCs thus promoting survival of tumor cells exposed to chemotherapeutic agents." (PMID 31861268, 2019). "To answer this question, we used the Cancer Cell Line Encyclopedia36 to identify tumour cell lines that express low (MCF7), medium (A549) and high (Hep3B) levels of JAG1, which we confirmed by immunoblotting." (PMID 29743479, 2018). "An in vitro transendothelial migration (iTEM) assay was used to examine the effects of short hairpin (sh)RNA targeting NRG1 in tumor cells and clustered regularly interspaced short palindromic repeats (CRISPR) knockout of jagged 1 (JAG1) in macrophages." (PMID 29636067, 2018).
tumor (continued). "Both JAG1 and DLL4 are up regulated in several cancer cells and can control neovascularization and stimulate tumor growth in mice." (PMID 28533486, 2017). "Both mDLL4 and JAG1 xenografts had an increased sensitivity to DBZ compared to EV-tumours, suggesting that Notch signalling is responsible for the enhanced tumour growth." (PMID 28445154, 2017). "JAG1, JAG2, HEY1 and HES1 had relatively higher expression in tumor samples compared to the pool of normal controls." (PMID 28146432, 2017). "To further investigate the interplay between JAG1 and DLL4 in promoting tumour growth, we used specific anti-DLL4 mAb (MedImm) that recognises both human DLL4 and mouse DLL4 to block DLL4-induced Notch signalling in mJAG1-expressing tumours." (PMID 28445154, 2017). "WB analyses of pooled tumor lysates showed that PC xenografts derived from leptin treated-tumorspheres had significantly higher levels of Notch4, DLL4, JAG1, survivin, PCNA and Oct-4." (PMID 27999190, 2017). "The following marker genes were differentially expressed in the triphasic tumours relative to the blastemal tumours: PA (LHX1), RV/CSB/SSB (BMP2, CDH6, JAG1, PAPSS2), ePT and/or imHL (CIDEB, CLIC6, UNC5CL, VDR), and early DT/imHL (KCNJ1)." (PMID 29040332, 2017). "The endostatin (E) and CTX (C)-treated samples exhibited almost similar expression levels for NOTCH-3, JAG-1, and DLL-4 that confirms the additive effect of the combination therapy against tumor angiogenesis." (PMID 26762567, 2016). "The result indicated JAG1 and HSPA2 were heterogeneously expressed in tumor parts and partially colocalized." (PMID 26930648, 2016). "In this study, we provide evidence that JAG1 is a direct target of KDM2A and is important for KDM2A to promote tumor stemness and angiogenesis." (PMID 27029061, 2016). "Several studies have reported that JAG1 mediates multiple signaling pathways such as: AP-1, MAPK, EGFR, NF-κβ, and IL-6 in different tumor cells." (PMID 26930648, 2016). "Interestingly, JAG1 has been reported not only to be expressed and to play a role in cancer cells but its expression and activity have also been described in other cell types present in the tumor microenvironment such as mesothelial and endothelial cells, astrocytes, and osteoblasts." (PMID 25309874, 2014). "JAG1 also co-operates with HPV16-E6 and E7 oncoproteins in cell transformation and during in vivo tumor growth." (PMID 25309874, 2014). "miR-34a was also reported to target Notch signaling pathway to inhibit tumor stem cell invasion by directly binding to NOTCH1, DLL1 and JAG1 as well as Wnt signaling pathway by targeting WNT1 and WNT3 genes and TGF-β signaling pathway via Smad4." (PMID 23823624, 2013). "Furthermore, lncRNA HOXA-AS2 has been shown to upregulate KDM2A by suppressing miR-302a, which increases Jagged 1 (JAG1) expression, potentially promoting GBM and regulatory T cell proliferation, facilitating immune tolerance and tumor progression." (PMID 40450300, 2025). "PRAT also modulates vascular endothelial growth factor A (VEGFA), vascular endothelial growth factor D (VEGFD), Jagged 1 (JAG1), and transforming growth factor β1 (TGF-β1) activity in the tumor niche, promoting tumor angiogenesis and, consequently, cancer cell growth and metastasis." (PMID 40227577, 2025). "Interestingly, the DEG enrichment of JAG1, DLL4, and all Notch receptors increased according to tumor stage." (PMID 39074091, 2024). "Overall, our findings suggest that JAG1 may affect the transcription of PDL1 by regulating the expression of VDR, leading to tumor immune escape, promoting tumor cell survival, and shortening patient survival." (PMID 38022677, 2023). "JAG1-NOTCH1 and TNFSF15-TNFRSF25 signals were present between tumor cells and low-risk T cells, and absent between tumor cells and high-risk T cells." (PMID 37120631, 2023).
tumor (continued). "Primary tumor cells have high levels of endogenously expressed Jag1, therefore we did not expect that exposure of exogenous Jag1 to these cells would cause significant effect on their phenotype." (PMID 37202533, 2023). "Studies using T cells that expressed these CARs demonstrated that one anti-JAG1 CAR induced effective T-cell activation in the presence of JAG1-positive but not JAG1 knockout tumor cells as well as the specific killing of JAG1-positive tumor cells." (PMID 36979394, 2023). "As ligands of the NOTCH receptor, JAG1 and DLL4 levels were analyzed in the PDAC tumor tissues." (PMID 35673567, 2022). "JAG1 was also statistically overexpressed in the tumor samples compared to the benign samples, regardless of race (p < 0.0001)." (PMID 35710817, 2022). "Finally, IHC showed that JAG1 was overexpressed in HCC tissues and was correlated with tumour size and number and tumour thrombus formation." (PMID 35349480, 2022). "Furthermore, we found that JAG1 and NOTCH1 silencing decreased the in vivo OSCC tumor burden and tumor weight, respectively." (PMID 35249111, 2022). "Furthermore, tumor volume and weight of BALB/c mice were lowered in response to lncRNA HOXA-AS2 silencing, while further JAG1 overexpression abrogated these trends." (PMID 35181676, 2022). "In this study, we found down-regulation of miR-512-5p may contribute to tumor progression, and further demonstrated that BMSC-derived exosomes delivering miR-512-5p could suppress GBM progression by negatively regulating JAG1." (PMID 33795521, 2021). "While Notch ligand–receptor interactions are rarely investigated in experimental studies, it has been confirmed that JAG1 may be critical for Notch/KRAS signaling and required to promote tumor aggressiveness." (PMID 33430387, 2021). "Moreover, treatment with soluble JAG1 resulted in the decreased differentiation of Treg cells, a decreased expression of PD-1 molecules on CD8+Tem cells and improved anti-tumor responses." (PMID 30940183, 2019). "We constructed a monovalent soluble JAG1 (sJAG1) construct comprising total five N-terminal domains (MNNL, DSL and 3 EGF repeats) of mouse JAG1, and evaluated the significance of JAG1-mediated Notch signaling in anti-tumor responses." (PMID 30940183, 2019). "Addition of an exogenous JAG1 peptide alone can significantly increase transendothelial migration of MDA-MB 231 cells, supporting the conclusion that stimulation of the Notch receptor on tumor cells by JAG1 can enhance intravasation." (PMID 29636067, 2018). "Jag1 antibody treatment reduces patient-derived tumor orthoxenograft growth without affecting normal intestinal mucosa." (PMID 30065304, 2018). "Endothelial JAG1 also antagonized DLL4 regulation of endothelial branching and increased vascular maturation downstream of DLL4-Notch1 in a skin wound healing model as well as promoted tumour growth through pro-angiogenic and angiocrine functions." (PMID 28445154, 2017). "We tested the ability of gal-3 to interfere with JAG1 and DLL4-induced tumor growth." (PMID 28533486, 2017). "Stains for THBS1, JAG1, and EDN1 were available in the protein atlas database for the same tumor and showed significant expression of all three genes from our CINP transcriptional module in the VM tumor tissue but little stain in healthy tissues." (PMID 29162797, 2017). "In addition to increase of stemness, we also demonstrated the promotion of tumor angiogenesis by KDM2A via PDGFA and JAG1." (PMID 27029061, 2016). "In addition to alteration in cell proliferation, our GSEA analysis demonstrated that inhibition of KDM2A attenuates tumor angiogenesis and mRNA expression of several genes in the NOTCH signaling pathway including JAG1, NOTCH1, HEY1." (PMID 27029061, 2016).
tumor (continued). "Next, we examined by qRT-PCR if FOXC2 knockdown in U2OS cells affects the expression of several genes known to be enriched in tumor-propagating cells, such as the cell surface marker CD133, multidrug resistance pump ABCG2, Notch signaling receptor ligands JAG1 and BMP4, and chemokine receptor CXCR4." (PMID 27634875, 2016). "Various tumor-derived factors have been previously shown to be functionally involved in osteolysis by directly stimulating osteoclast differentiation, including secreted factors like RANKL, GM-CSF or PTHrP, as well as cell surface ligand jagged 1 (JAG1)." (PMID 25973542, 2015). "Silencing of stromal-expressed Jag1 also impaired tumor growth, without affecting tumor cell proliferation, by reducing the microvascular density." (PMID 25309874, 2014). "The result implies that concurrent activation of JAG1 or NOTCH1 downstream pathway with TGFβ signaling is important in the process of invasion and metastasis; however, it might be disadvantageous for the progression of the bulk of the tumor." (PMID 39074091, 2024). "The CD46-JAG1 ligand-receptor interaction occurred in epithelial cells and endothelial cells was obvious in JAG1-positive group, which suggested that targeting CD46 in tumor cells may decrease the expression of JAG1, thereby reducing the immunosuppressive phenotype." (PMID 36923423, 2023). "Regulation of Notch signaling by the tumor architecture, in this case the activation of HEYL transcription by JAG1 and JAG2 expression in neighboring cells, is also observed in other types of cancers, such as basal cell carcinoma and might be an important criterion in CRC." (PMID 37860822, 2023). "However, upregulated JAG1 was observed in tumor tissues of BALB/c mice treated with oe-JAG1 along with no significant alterations in the lncRNA HOXA-AS2, KDM2A and miR-302a expression in the presence of sh-lncRNA HOXA-AS2." (PMID 35181676, 2022). "Additionally, the crosstalk between tumor cells and dendritic cells, which is necessary for the generation and proliferation of T regulatory (Treg) cells in the TME, is significantly influenced by JAG1-induced Notch activation." (PMID 36229883, 2022). "In the tumor microenvironment of BC, a secreted protein named Cartilage Oligomeric Matrix Protein (COMP) physically bridges Notch3 and JAG1 on the cell membrane of CSCs, thus driving JAG1/Notch3 signaling and subsequently activating the β-catenin and Akt signaling pathways to maintain CSC status." (PMID 34195229, 2021). "In addition, Jagged-1 (JAG1) is a canonical ligand that activates Notch signaling that has been reported to be strongly upregulated in different cancers, including CRC, promoting tumor progression, angiogenesis and recurrence." (PMID 34067294, 2021). "Therefore, inhibition of HER2 followed by inhibition of JAG1 or NOTCH1 may be more effective in preventing drug resistance and tumor progression than a simultaneous blockade." (PMID 34374886, 2021). "DLL4 activates Notch signaling in the stalk ECs to inhibit sprouting angiogenesis and results in fewer but larger vessels, whereas JAG1 mainly increases sprouting angiogenesis and enhances the amount rather than the size of vessels by signaling to tumor cells and ECs." (PMID 32046779, 2020). "JAG1 is not antagonistic but utilises DLL4 in tumour angiogenesis." (PMID 28445154, 2017). "The tumor inhibition rate was evaluated, followed by the quantification of messenger ribonucleic acid (mRNA) and protein expression of notch signaling components NOTCH-1, NOTCH-3, NOTCH-4, JAG-1, DLL-4, Hes-1, and Hey-1 using quantitative polymerase chain reaction (qPCR)." (PMID 26762567, 2016). "JAG1 was mostly cytoplasmic in tumour cells and is thus unlikely to contribute to trans-signalling." (PMID 25167871, 2014). "All these points suggest that JAG1-targeted therapies could be of benefit to cancer patients even in the absence of tumoral JAG1 expression due to its role in tumor angiogenesis." (PMID 25309874, 2014).